ZFP62 (ZFP62 zinc finger protein)
Description:
May play a role in differentiating skeletal muscle.
Synonyms: FLJ34231; ZET; ZNF755
Tractability: PROTAC: UniProt records ubiquitination sites on it; ubiquitination databases record sites on it; its protein half-life has been measured.
Gene: Protein-coding gene on chromosome 5 (180,847,611 to 180,861,285, reverse strand). Ensembl gene ENSG00000196670.
Subcellular location: Nucleus
Subcellular location (Human Protein Atlas): Nucleoplasm; Actin filaments
Gene Ontology:
Molecular function: transcription cis-regulatory region binding
Biological process: regulation of transcription by RNA polymerase II
Cellular component: nucleus; cytoplasm
Genetic constraint (gnomAD): Loss-of-function variants: 45 observed, 54.73 expected, observed/expected ratio (o/e) 0.82, 90% interval 0.65 to 1.05. The upper end of that interval is the gene's LOEUF score, 1.05, which puts it in group 4 of 6, group 1 being the genes least tolerant of losing a copy. Missense variants: 1,030 observed, 1,062.2 expected, observed/expected ratio (o/e) 0.97, 90% interval 0.92 to 1.02. Synonymous variants: 421 observed, 378.53 expected, observed/expected ratio (o/e) 1.11, 90% interval 1.03 to 1.21.
Homologues: Orthologues: chimpanzee ZFP62 (99% identical), macaque ZFP62 (97% identical), pig ZFP62 (92% identical), dog ZFP62 (92% identical), rabbit ZFP62 (91% identical), rat Zfp62 (88% identical), mouse Zfp62 (87% identical), guinea pig ZFP62 (85% identical), Drosophila melanogaster CG18476 (23% identical), Drosophila melanogaster CG10669 (20% identical). Paralogues in human: ZNF808 (38% identical), ZNF721 (34% identical), ZNF485 (20% identical), ZNF648 (17% identical), ZNF664 (15% identical).
Diseases named in the same sentence as ZFP62 in open-access papers:
ZFP62 is named in the same sentence as 1 disease in open-access papers, as found by Europe PMC text mining. Sharing a sentence is not in itself a finding about the gene and the disease. The quoted sentences say what the papers report.
COVID-19 (1 paper, 2023). A disease caused by infection with severe acute respiratory syndrome coronavirus 2. "An interesting predicted DTI is artenimol, an antimalarial agent targeting ZFP62, one of our newly identified COVID-19-related genes." (PMID 36674947, 2023). "Our most interesting prediction is artenimol, an antimalarial agent targeting ZFP62, one of our newly identified COVID-19-related genes." (PMID 36674947, 2023). "For the two newly predicted COVID-19-related genes, ZFP62 and ZNF286A, there do not exist any drugs targeting their gene products." (PMID 36674947, 2023).